WNT3A (Wnt family member 3A)
Diseases named in the same sentence as WNT3A in open-access papers (continued):
Sharing a sentence is not in itself a finding about the gene and the disease.
colon carcinoma (continued). "Demethoxycurcumin and bisdemethoxycurcumin suppress β-catenin transcription activated by Wnt3a-conditioned medium and inhibit the growth of various colon cancer cells." (PMID 26369691, 2015). "VM-positive colon cancer samples showed increased Wnt3a expression (p < 0.001) and β-catenin nuclear expression (p < 0.001) compared with the VM-negative samples." (PMID 26266404, 2015). "PLD is necessary for the Wnt3a-driven invasion and anchorage-independent growth of colon cancer cells." (PMID 26369691, 2015). "In this study, the expression patterns of Wnt3a, β-catenin, and VM were examined on a large array of 217 human colon cancer cases." (PMID 26266404, 2015). "Recently, Boutros reported that sustained wnt activity through wnt3a and Evi/Wls/GPR177 can be important for the proliferation in colon cancer cell, independently from APC or β-catenin mutation." (PMID 24564183, 2014). "We also investigated cell proliferation and invasion in cell cultures with Wnt3a overexpression, as well as tumor growth and metastasis in a colon cancer xenograft model." (PMID 25499541, 2014). "In conclusion, we showed that Wnt3a expression activated the Wnt/β-catenin signaling pathway, and this activation was a mechanism underlying EMT in colon cancer." (PMID 25499541, 2014). "Although the effects of Wnt/β-catenin signaling in promoting EMT during physiological or pathological processes have been extensively studied, the present study was the first to demonstrate the EMT-inducing ability of Wnt3a in colon cancer." (PMID 25499541, 2014). "We then upregulated Wnt3a expression in HCT116 colon cancer cells, established a nude mouse xenograft model, detected the expression of EMT and Wnt/β-catenin signaling-associated proteins, and observed invasion and clone-initiating abilities." (PMID 25499541, 2014). "In the present study, we initially analyzed Wnt3a expression in a large array of colon cancer tissue samples to determine its role in colon-cancer progression." (PMID 25499541, 2014). "To assess the relationship between Wnt3a and EMT in colon cancer, we investigated the expression of the EMT-associated markers E-cadherin, vimentin, and β-catenin (also a marker of Wnt/β-catenin pathway activation)." (PMID 25499541, 2014). "We established stable Wnt3a-overexpressed colon cancer cells to study the EMT-promoting effect of Wnt3a on colorectal cancer cells." (PMID 25499541, 2014). "EMT induction in colon cancer cells by Wnt3a was confirmed through the altered morphology and expression of the EMT-associated markers, as well as enhanced invasion capacities." (PMID 25499541, 2014). "The effects of Wnt3a ectopic expression in the colon cancer cell line HCT116 on the expression of epithelial and mesenchymal markers and EMT transcription factors were studied." (PMID 25499541, 2014). "Here we show that PLD is necessary for Wnt3a-driven invasion and anchorage-independent growth of colon cancer cells." (PMID 20711340, 2010). "WNT-3a and β-catenin were downregulated in colon cancer cell lines." (PMID 36904007, 2023). "Furthermore, Wnt3a is substantially enhanced in colon cancer cells in promoting tumour angiogenesis and metastasis." (PMID 36611811, 2022). "In addition, it has been described that colon carcinoma cells acquire the ability to secrete canonical Wnt proteins such as Wnt3A to autocrinally achieve high activation of the Wnt/β-catenin signalling pathway and increase their own survival." (PMID 31147591, 2019). "In summary, our findings reinforce the relevance of 1,25(OH)2D3 and Wnt3A in healthy and pathologic intestine, and indicate that in addition to their action on intestinal normal epithelial cells and on colon carcinoma cells, they are strong regulators of colon fibroblast biology." (PMID 31147591, 2019). "Whether BRG1 promotes colon cancer progression through positive regulation of WNT3A is still unknown." (PMID 27852072, 2016).
colon carcinoma (continued). "In addition, BRG1 contributes to colon cancer proliferation and invasion through positive regulation of WNT3A expression." (PMID 27852072, 2016). "In this study, we demonstrated that BRG1 activates WNT3A expression in colon cancer cells." (PMID 27852072, 2016). "In this study, we demonstrate that BRG1 may contribute to colon cancer progression through upregulating WNT3A expression." (PMID 27852072, 2016). "In vitro, over-regulated Wnt3a expression in HT29 colon cancer cells promoted the capacity to form tube-like structures in the three-dimensional (3-D) culture together with increased expression of endothelial phenotype-associated proteins such as VEGFR2 and VE-cadherin." (PMID 26266404, 2015). "The mitogen activated and extracellular regulated kinase (MEK) inhibitor PD98059, genistein, and wortmannin effectively suppress Wnt3a/β-catenin–regulated transcriptional activities as well as the intracellular accumulation of β-catenin protein in human colon cancer cells." (PMID 26369691, 2015). "The Wnt3a secreted by colon cancer cells could activate Wnt signaling in AMSCs and induce AMSCs to trigger the secretion of a select set of proteins, converge on and increase the expression of the stemness transcriptional factors and EMT-associated genes." (PMID 26060426, 2015). "All results indicated that the EMT-inducing effect of Wnt3a in colon cancer may be at least partially due to the stimulative effect of Wnt3a on the Wnt/β-catenin pathway." (PMID 25499541, 2014). "The expression levels of Wnt3a and EMT-associated proteins (E-cadherin, vimentin, and β-catenin) were assessed by immunohistochemistry in human colon cancer tissues to evaluate the clinicopathological significance of Wnt3a, as well as the correlation between Wnt3a and EMT." (PMID 25499541, 2014). "Wnt3a expression was associated with EMT and promoted colon cancer progression." (PMID 25499541, 2014). "Wnt3a expression level in colon cancer was found to increase with decreased differentiation grade." (PMID 25499541, 2014). "In addition, restoration of WNT3A expression promotes invasion in colon cancer cells (**P < 0.01)." (PMID 27852072, 2016). "For instance, in colon cancer cell lines it has been demonstrated that RES reduces the expression of regulators of β-catenin localization which leads to the reduced β-catenin protein content that attenuates the Wnt pathway even in presence of Wnt3a (Wnt pathway activator)." (PMID 27980591, 2016). "Differences in Wnt3a expression level within tumors were found, with strong Wnt3a expression observed in tumor cells located close to stroma, implicating that Wnt3a may be involved in tumor progression in colon cancer." (PMID 25499541, 2014). "In 203 human colon cancer tissue samples, Wnt3a protein overexpression was related to colon cancer histological differentiation (P = 0.004), clinical stage (P = 0.008), presence of metastasis and recurrence (P = 0.036), and survival time (P = 0.007) of colon cancer patients." (PMID 25499541, 2014). "Indeed, recently it has been reported that using Wnt3a and Wnt5a as prototype ligands to activate the canonical or the non-canonical pathways, respectively, promotes sphere-formation capacity and proliferation through the β-catenin-independent manner in colon cancer cells." (PMID 37804416, 2024). "In MGC-803 and BGC-823 gastric cancer cells, Hep-3B hepatocarcinoma cells and Caco2 colon cancer cells, the levels of H3K4 me1/2 and H3K27 me3 were decreased, and those of H3K4 me3 and H3K27 me1/2 were increased with 100 ng/ml Wnt3a treatment for 24 hours." (PMID 27121204, 2016). "The baseline activities of canonical Wnt signaling in colon cancer cell lines and colorectal carcinoma (CRC) tissues were examined by accessing the expression of Wnt3a and β-catenin." (PMID 26060426, 2015).
colon carcinoma (continued). "The diterpenoid derivative 15-oxospiramilactone suppresses Wnt3a-stimulated top-flash reporter activity in HEK293T cells and inhibits the growth of colon cancer SW480 and Caco-2 cells." (PMID 26369691, 2015). "We observed a significant correlation between Wnt3a expression and histological differentiation, clinical stages, metastasis, and recurrence, indicating that the upper stream factor of the Wnt signaling pathway may play an important role in colon-cancer progression." (PMID 25499541, 2014). "In this study, we evaluated the clinicopathological significance of Wnt3a and analyzed the correlation between Wnt3a expression and EMT immunohistochemical features in tissue specimens from 203 colon cancer patients." (PMID 25499541, 2014). "The colon cancer cell line, RKO, responded to Wnt3a CM, Wnt2 and Wnt1 by increasing canonical Wnt pathway throughput." (PMID 17386109, 2007). "Immunohistochemical staining also showed similar results that patients whose localized colon tumors were BRG1-strong had a significantly higher WNT3A expression than those with BRG1 negative/weak tumors." (PMID 27852072, 2016). "More abundant β-catenin and/or Wnt3a transcripts were observed in colon cancer LS174T, SW480 and HCT116 cells and CRC tissues, but not LoVo cells as compared with the normal colonic epithelial cell line CCD-18Co." (PMID 26060426, 2015). "At the same time, the over-expression of Wnt3A (Wnt is the representative of the Wnt ligand) can change the cell morphology by stimulating the Wnt/β-catenin signaling pathway, regulating the expression of EMT-related proteins, and accelerating the metastasis and progress of colon cancer." (PMID 37509109, 2023). "Therefore, in addition to the well characterized role of TGF-β, Wnt-3a and Hh pathways may further drive CLIC4 expression in CAFs as in SSc fibroblasts and colon cancer cells that are shown here." (PMID 35159339, 2022). "Whereas normal colon and rectum organoids were dependent on Wnt3a, R-Spondin, and nicotinamide, rectal tumor organoids (such as colon tumor organoids) could be grown in the absence of these factors." (PMID 32824266, 2020). "In human colon cancer tissue samples, lower levels of E-cadherin expression, as well as higher levels of vimentin expression and β-catenin nuclear distribution, were observed in the Wnt3a strong group than in the weak and negative expression groups." (PMID 25499541, 2014). "Using the prototype non-canonical ligand, Wnt5a, in comparison with Wnt3a, the prototype of a canonical β-catenin activating ligand, we describe here that non-canonical Wnt/Ca2+ cascade plays an essential role in inducing and maintaining the self-renewal capacity of colon cancer stem cells." (PMID 36969011, 2023). "Our results show that established colon cancer cell lines can be cultured in 3-D matrigel, and like their original source, human CRC, do not require the presence of EGF, R-Spondin1, Wnt3a, or Noggin for proliferation and long term expansion." (PMID 23638973, 2013). "Wnt2, but not Wnt3a, abrogated Fz4 expression in NCM460, but not in RKO or another colon cancer cell line, HCT116." (PMID 17386109, 2007). "However, the roles of Wnt3a, the representative canonical Wnt ligand, in EMT and colon cancer progression have not yet been fully explored." (PMID 25499541, 2014).
colorectal cancer (37 papers, 2010 to 2025). A primary or metastatic malignant neoplasm that affects the colon or rectum. "Thus, elevated expression of Wnt3A has been found in human colorectal carcinomas associated with advanced stages and worse prognosis." (PMID 31147591, 2019). "As a transcription regulation factor, we demonstrated that BRG1 participates in colorectal cancer metastasis by regulating Wnt3a." (PMID 35590122, 2022). "TGM2-siRNA knockdown attenuated colorectal cancer cell growth through the wnt3a/β-catenin/cyclin D1 pathway." (PMID 34202278, 2021). "This research aimed to relate the immunostaining of colorectal cancer samples forCDX2, beta-catenin and Wnt3a with the presence of disease progression and evolutionto death." (PMID 33331430, 2020). "Substantial studies report Wnt3a expression to be significantly correlated with colorectal carcinoma’s clinical staging, metastasis and recurrence." (PMID 31351496, 2019). "Here, we show that SMAR1 is highly downregulated during aberrant Wnt3a signaling due to proteasomal degradation and predicted poor prognosis of colorectal cancer." (PMID 29765542, 2018). "NCB-0846 inhibited the TCF/LEF transcriptional activity of Wnt3a-treated HEK293 and HCT116 (carrying CTNNB1 mutation) and DLD-1 (carrying APC mutation) colorectal cancer cells." (PMID 27562646, 2016). "Further investigation of the CM revealed that CD81+ exosomes were present and that these exosomes were acting on the colorectal cancer-derived stem cells via Wnt3a signaling." (PMID 27515302, 2016). "We established stable Wnt3a-overexpressed HT29 cells to further study the VM-promoting effect of canonical Wnt signaling on colorectal cancer cells." (PMID 26266404, 2015). "Wnt3a and wnt5a are highly expressed in colorectal cancer both in primary and metastatic sites with a higher than 50% concordance rate." (PMID 24564183, 2014). "It has been shown that Wnt3a promotes VM formation in colorectal cancer and breast cancer." (PMID 37407689, 2023). "Recently, WNT3A-mediated activation of PI3K was demonstrated in colorectal cancer cells." (PMID 37856394, 2023). "In line with the knockdown data, Gαi2 expression inhibited in a dosage-dependent manner both the Wnt3a-induced signaling in cells with otherwise low pathway activity and the basal Wnt signaling in colorectal cancer cell lines with high endogenous pathway activity." (PMID 35115535, 2022). "Since APC is mutated in >80% of colorectal cancers and is a major scaffolding protein for the β-catenin destruction complex, we first asked whether APC redistributes toward a localized Wnt3a signal in a panel of human CRC cell lines." (PMID 32076059, 2020). "Wnt3a expression is significantly associated with lymph node involvement and matrix metallopeptidase-9 (MMP-9) expression in primary tumor, mesenchyme adjacent to tumor, and metastatic sites in colorectal cancer." (PMID 26369691, 2015). "For example, some colorectal cancers have mutations in the Wnt pathway and can survive in environments without Wnt3a, so colorectal cancer organoids can be picked from normal organoids by removing the Wnt3a factor from the culture medium during the culture process." (PMID 37016422, 2023). "We then investigated the effects of PKN1 and PKN2 siRNAs on WNT3A-dependent AXIN2 expression in osteosarcoma (U2OS), and colorectal carcinoma (RKO) cell lines." (PMID 24114839, 2013). "The tumor markers CDX2, beta-catenin and Wnt3a were not good instruments to assessthe chance of disease progression or the possibility of evolution to death in thecontext of colorectal cancer." (PMID 33331430, 2020). "Wnt3a can enhance the expression and activity of phospholipase D1 (PLD1; a cell survival mediator) in many types of cancer cells and enhance the expression of PLDs at a transcriptional level, as shown in colorectal cancer HCT116 cells." (PMID 26369691, 2015).
colorectal cancer (continued). "Wnt3a and Wnt mimetics significantly enhanced the expression of PLDs at a transcriptional level in HCT116 colorectal cancer cells, whereas silencing of β-catenin gene expression or utilization of a dominant negative form of T cell factor-4 (TCF-4) inhibited expression of PLDs." (PMID 20711340, 2010). "Meanwhile, the role of Wnt3a in colorectal cancer EMT has not been fully explored." (PMID 25499541, 2014). "In this context, we evaluated whether lonchocarpin, a chalcone isolated from Lonchocarpus sericeus, is able to inhibit the Wnt signaling pathway in human colorectal cancer cell lines RKO pBAR/Renilla stimulated with Wnt3a CM (conditioned medium) for 24 h and non-stimulated SW480 pBAR/Renilla." (PMID 31817828, 2019). "However, the roles of wnt3a and wnt5a in colorectal cancer (CRC) have not been thoroughly studied." (PMID 24564183, 2014). "TOPflash assays were performed in 293T cells with or without exogenous Wnt3a and R-spondin 3 (i.e., Wnt pathway on or off), as well as in HCT116 colorectal cancer cells with constitutively active Wnt signaling." (PMID 37011861, 2023). "However, in HCT116 colorectal cancer cells, knockdown of CTNNB1 did not increase TCF7L1 protein levels, and CTNNB1 stabilization by addition of Wnt3a showed only a modest decrease in TCF7L1 protein." (PMID 27333864, 2016).